LGMN (legumain)
Description:
Has a strict specificity for hydrolysis of asparaginyl bonds. Can also cleave aspartyl bonds slowly, especially under acidic conditions. Involved in the processing of proteins for MHC class II antigen presentation in the lysosomal/endosomal system. Also involved in MHC class I antigen presentation in cross-presenting dendritic cells by mediating cleavage and maturation of Perforin-2 (MPEG1), thereby promoting antigen translocation in the cytosol (By similarity). Required for normal lysosomal protein degradation in renal proximal tubules (By similarity). Required for normal degradation of internalized EGFR (By similarity). Plays a role in the regulation of cell proliferation via its role in EGFR degradation (By similarity).
Synonyms: AEP; PRSC1; LGMN1
Tractability: Small molecule: a structure with a bound ligand is known; a high-quality ligand is known. Antibody: its Gene Ontology location is reachable by antibodies, with high confidence; UniProt predicts a signal peptide or a membrane-spanning region. PROTAC: ubiquitination databases record sites on it; its protein half-life has been measured; a small molecule that binds it is known.
Target class: Cysteine protease CD clan; Cysteine protease; Cysteine protease C13 family; Enzyme; Protease
Gene: Protein-coding gene on chromosome 14 (92,703,798 to 92,751,131, reverse strand). Ensembl gene ENSG00000100600.
Subcellular location: Lysosome
Subcellular location (Human Protein Atlas): Vesicles; Nucleoplasm
Pathways (Reactome):
Immune System: MHC class II antigen presentation; Trafficking and processing of endosomal TLR
Metabolism: Vitamin D (calciferol) metabolism
Gene Ontology:
Molecular function: cysteine-type endopeptidase activity; endopeptidase activator activity; peptidase activity; tau protein binding
Biological process: antigen processing and presentation of exogenous peptide antigen via MHC class II; cellular response to amyloid-beta; cellular response to calcium ion; cellular response to hepatocyte growth factor stimulus; negative regulation of gene expression; negative regulation of neuron apoptotic process; positive regulation of cell population proliferation; positive regulation of endothelial cell chemotaxis; positive regulation of mitotic cell cycle; positive regulation of monocyte chemotaxis; response to acidic pH; associative learning; dendritic spine organization; memory; negative regulation of ERBB signaling pathway; positive regulation of long-term synaptic potentiation; protein catabolic process; protein maturation; proteolysis; receptor catabolic process; renal system process; vitamin D metabolic process
Cellular component: cytoplasm; extracellular exosome; extracellular region; lysosomal lumen; lysosome; perinuclear region of cytoplasm; endolysosome lumen; late endosome; apical part of cell
Genetic constraint (gnomAD): Loss-of-function variants: 20 observed, 34.12 expected, observed/expected ratio (o/e) 0.59, 90% interval 0.41 to 0.85. The upper end of that interval is the gene's LOEUF score, 0.85, which puts it in group 3 of 6, group 1 being the genes least tolerant of losing a copy. Missense variants: 354 observed, 425.95 expected, observed/expected ratio (o/e) 0.83, 90% interval 0.76 to 0.91. Synonymous variants: 160 observed, 165.53 expected, observed/expected ratio (o/e) 0.97, 90% interval 0.85 to 1.1.
Homologues: Orthologues: chimpanzee LGMN (99% identical), macaque LGMN (99% identical), pig LGMN (85% identical), mouse Lgmn (83% identical), rat Lgmn (83% identical), guinea pig LGMN (82% identical), rabbit LGMN (79% identical), dog LGMN (70% identical), tropical clawed frog lgmn (68% identical), zebrafish lgmn (65% identical), Caenorhabditis elegans lgmn-1 (42% identical). Paralogues in human: PIGK (22% identical).
Diseases named in the same sentence as LGMN in open-access papers:
LGMN is named in the same sentence as 113 diseases in open-access papers, as found by Europe PMC text mining. Sharing a sentence is not in itself a finding about the gene and the disease. The quoted sentences say what the papers report.
breast carcinoma (25 papers, 2013 to 2025). "A relationship has been found between the secretion of human legumain zymogen and the progression of metastasis in human breast cancer, and the secretion of the mature form has been linked to carotid atherosclerosis." (PMID 38392857, 2024). "Breast cancer, stomach cancer, and other malignancies have all been linked to LGMN expression and distribution." (PMID 36825203, 2023). "For example, in breast cancer, legumain is expressed in tissue-associated macrophages (TAMs) as well as in stromal cells, and its circulating levels are significantly increased, leading to the promotion of cancer-cell proliferation and metastasis." (PMID 36555634, 2022). "Moreover, legumain is involved in the production of oxygen reactive species and metastasis in breast cancer, which is counteracted by legumain deficiency or inhibition." (PMID 36555634, 2022). "Expression of legumain, an endo-lysosomal cysteine protease, is positively correlated with metastatic progression and poor prognosis in breast cancer." (PMID 41294885, 2025). "It was constructed a mouse model of breast cancer with LGMN gene deletion by knocking out the LGMN gene in TAMs and found that tumor growth was significantly inhibited." (PMID 36825203, 2023). "Legumain (LGMN), an endo-lysosomal cysteine protease, has been found to exhibit a positive correlation with the metastatic progression of breast cancer." (PMID 37681860, 2023). "Limited legumain expression can be detected in normal tissues, whereas numerous human cancers, such as ovarian cancer, colorectal cancer, prostate cancers, gastric carcinoma, and breast cancers are known to express elevated levels of legumain." (PMID 35203212, 2022). "Legumain was demonstrated overexpressing in various cancers, such as breast cancer, colorectal cancer, and prostate cancer, whereas rarely expressed in normal tissues." (PMID 35638851, 2022). "According to reports, legumain is overexpressed at a quite high level in several cancers, including breast cancer, colorectal cancer and gastric cancer." (PMID 35631369, 2022). "In contrast, the endogenous legumain inhibitor cystatin E/M is considered a breast cancer suppressor." (PMID 36555634, 2022). "Legumain (LGMN) is highly expressed in breast cancer (BC) and other solid tumors and is a potential anticancer target." (PMID 27656894, 2016). "We show for the first time that TBX2 mediated transcriptional repression of CST6 is an important event for maintaining the tumorigenesis of a subset of breast cancers, through aberrant activation of the protease LGMN." (PMID 24742492, 2014). "LGMN is a known oncogene, an indicator of poor prognosis in colorectal and breast cancers and has been reported to be overexpressed in the majority of human solid tumors." (PMID 24742492, 2014). "Legumain was found to be highly expressed in several types of tumors, such as colon, prostate and breast cancers." (PMID 24023813, 2013). "A zymogenic form of legumain is secreted by motile breast cancer cells." (PMID 41294885, 2025). "Interestingly, increased expression and tumor promoting function of LGMN have been reported in several carcinomas previously such as cervical cancer, gastric cancer, oral cancer, breast cancer, neuroblastoma, pancreatic cancer, ovarian cancer and melanoma." (PMID 38980440, 2024). "Motile breast cancer cells secrete legumain in its zymogen form." (PMID 37681860, 2023). "Similarly, It was found through immune histochemistry that the higher the expression of LGMN in breast cancer, the higher the tumor grade." (PMID 36825203, 2023). "Then, the legumain-sensitive site of PTX-released PPP (mPEG-PTP-7) was exposed and cut by legumain overexpressed in breast carcinoma and colorectal carcinoma, such as MCF-7, 4T1, and HCT116 cancer, and finally releases PTP-7 to kill the tumor cell by cracking cell membrane." (PMID 35638851, 2022).
breast carcinoma (continued). "LGMN has been determined to be highly expressed in many solid tumors, including colorectal cancer, breast cancer and glioblastoma (GBM), and high expression of LGMN correlated with a more metastatic phenotype, which is partially mediated by the activation of cathepsins and pro-MMP2." (PMID 34966781, 2021). "We suggest that the development of cell permeable LGMN inhibitors may be an important advance in the clinical management of poor prognosis breast cancers and multiple other tumor types." (PMID 24742492, 2014). "The apparent ‘addiction’ to LGMN for cell survival that we have observed in breast cancer cell lines and the high activity of LGMN previously reported across a range of cancer types has made targeting this enzyme an attractive prospect for the development of novel inhibitors." (PMID 24742492, 2014). "Legumain, an endo-lysosomal cysteine protease, interacts with integrin αvβ3 through the RGD motif and has been shown to suppress breast cancer cell migration and invasion." (PMID 41294885, 2025). "Knockdown of LGMN and the only other known AEP enzyme (GPI8) by siRNA confirmed that LGMN was the enzyme responsible for maintaining breast cancer proliferation." (PMID 24742492, 2014). "The LGMN AEPI (Aza-Asn epoxides significantly block the activity of AEP) inhibitors, on the other hand, confirmed that the LGMN protein might influence the expansion and migration of breast cancer cells." (PMID 36825203, 2023). "Legumain-specific targeting therapy, using nanoparticles, has been effective for breast cancer in a mouse model without significant toxicity." (PMID 35203212, 2022). "In addition to caspase, linkers that can respond to legumain, a biomarker overexpressed in several cancers such as breast cancer, gastric cancer, colorectal cancer, have been developed for PET imaging of legumain activity and diagnosis of legumain‐related diseases." (PMID 39175888, 2024).
Alzheimer disease (20 papers, 2017 to 2025). A progressive, neurodegenerative disease characterized by loss of function and death of nerve cells in several areas of the brain leading to loss of cognitive function such as memory and language. "Finally, dysregulated legumain activity is associated with cancer and neurodegenerative diseases, including Alzheimer's disease (AD), stroke, ischemia, amyotrophic lateral sclerosis (ALS), and multiple sclerosis." (PMID 35067006, 2022). "In the context of Alzheimer’s disease, legumain phosphorylation at S226 by SRPK2 led to accumulation of cytoplasmic legumain, promoting cleavage of tau, APP, and SRPK2 itself." (PMID 38199506, 2024). "The asparaginyl endopeptidase legumain is upregulated in neurons in Alzheimer's disease and in posttraumatic neurodegeneration." (PMID 38062768, 2023). "Under pathophysiologic conditions such as Alzheimer’s disease and cancer, the endolysosomal cysteine protease legumain was found to translocate to the cytosol, the nucleus, and the extracellular space." (PMID 36116553, 2022). "Given the role of legumain in the pathogenesis of Alzheimer’s disease and Parkinson’s disease, it is possible that legumain inhibition contributes to the beneficial effects of statins in these neurodegenerative diseases." (PMID 36555634, 2022). "C/EBPꞵ has been shown to regulate legumain expression in the brain in an age-dependent manner, thereby contributing to the pathogenesis of Alzheimer’s disease." (PMID 36555634, 2022). "Cystatins are twin-headed inhibitors, simultaneously targeting the lysosomal cathepsins and legumain, with important roles in cancer progression and Alzheimer's disease." (PMID 29967063, 2018). "Moreover, an increasing number of studies have suggested that legumain is involved in a variety of inflammatory diseases, such as atherosclerosis, pancreatitis, atherosclerosis, and Alzheimer's disease 30-32." (PMID 40027188, 2025). "δ-secretase, also known as asparagine endopeptidase (AEP) or legumain, is a lysosomal cysteine protease that cleaves both amyloid precursor protein (APP) and tau, mediating the amyloid-β and tau pathology in Alzheimer's disease (AD)." (PMID 28345579, 2017).
gastric cancer (20 papers, 2013 to 2025). A primary or metastatic malignant neoplasm involving the stomach. "Research has revealed that the expression of legumain is positively related to the risk of distant metastasis in gastric cancer patients." (PMID 40027188, 2025). "LGMN expression is also considered as an independent prognostic factor for the overall survival rate of patients with gastric cancer and increased LGMN expression was significantly associated with peritoneal metastasis." (PMID 38980440, 2024). "Cumulatively, our results indicate that loss of miR-3978 leads to increased expression of legumain, which indicates that miR-3978might be a biomarker for peritoneal metastasis in patients with gastric cancer." (PMID 27793040, 2016). "Notably, LGMN overexpression is correlated with aggressive tumor phenotypes and poor prognosis in colorectal and gastric cancers, whereas reduced LGMN expression has been linked to improved clinical outcomes." (PMID 41375125, 2025). "Association between Legumain expression and clinicopathologic factors in gastric cancers." (PMID 24023813, 2013). "Legumain expression could serve as a prognostic biomarker in patients at risk of developing metastasis or recurrence with gastric carcinoma." (PMID 24023813, 2013). "Given that our experiments indicated that legumain is a bona-fide target of miR-3972, we hypothesized that suppression of miR-3978 expression might be an underlying feature of peritoneal metastasis pathogenesis in patients with gastric cancer." (PMID 27793040, 2016). "Helicobacter pylori was recently shown to induce secretion of the lysosomal protease legumain to promote cleavage of extracellular matrix proteins and subsequent tumour invasion in a gastric cancer model." (PMID 40274809, 2025). "In conclusion, our results demonstrated that gastric cancer exhibits a higher expression of LGMN and secretes LGMN extracellularly." (PMID 39065799, 2024). "Legumain, encoded by the LGMN gene located on human chromosome 14, has been identified in various tumors such as breast and gastric cancers where it is associated with tumor aggressiveness, migratory behavior, and poor prognosis." (PMID 39543114, 2024). "In recent years, legumain has been found to be overexpressed in a variety of solid tumor tissues, including colorectal, breast, ovarian, prostate and gastric cancer, and was highly correlated with tumor growth, invasion and metastasis." (PMID 36797792, 2023). "Legumain (AEP) was reported to promote the invasion and metastasis of gastric cancer cells by modulating EMT and promoting β-catenin expression." (PMID 36797792, 2023). "LGMN over expression has been shown to increase tumor cell migration and invasion in vitro using cell lines derived from ovarian and stomach cancers." (PMID 36825203, 2023). "Expression of both PCBP1 and miR-3978 is downregulated whereas expression of legumain is upregulated in gastric cancer patients with peritoneal metastasis." (PMID 30246786, 2018). "Our results indicated a dynamic and inverse correlation between down-regulation in the levels of miR-3978 and the observed increase in legumain protein expression in metastatic gastric cancer tissue specimens (P <.005, Pearson correlation r = −0.8761)." (PMID 27793040, 2016). "We determined miR-3978 and legumain protein expression in 20 gastric cancer patients with different stages of peritoneal metastasis." (PMID 27793040, 2016). "In the current study, our experimental results show that miRNA-3978 and legumain is downregulated and upregulated, respectively, in gastric cancer patients with peritoneal metastasis." (PMID 27793040, 2016). "Our results suggested that miR-3978 expression can inhibit in vitro migration and invasion in gastric cancer, which occurs by repression of LGMN expression." (PMID 27793040, 2016). "To explore the mechanism(s) regulating legumain expression, we first evaluated legumain expression in peritoneal metastatic samples obtained from gastric cancer patients." (PMID 27793040, 2016).
gastric cancer (continued). "The miR-3978 mimic inhibited gastric carcinoma and metastatic progression in a mice model by regulating legumain protein expression." (PMID 27793040, 2016). "We examined the expression of Legumain in nodal metastasis as in the primary gastric cancer specimens." (PMID 24023813, 2013). "Lymph node metastasis is a key step in the metastatic cascade in gastric cancer, we evaluated Legumain expression in matched primary gastric cancer and lymph node metastatic sites." (PMID 24023813, 2013). "Of the 98 cases of metastasis lymph nodes analyzed, 35 samples (35.7%) showed Legumain over-expression compared with the paired primary gastric cancer, of which 45% showed Legumain over-expression (P<0.001)." (PMID 24023813, 2013). "In this study, a tissue microarray (TMA) containing 282 samples of primary gastric cancer was assessed for Legumain expression by immunohistochemistry." (PMID 24023813, 2013). "This strong correlation suggests that Legumain can be used as a biomarker to identify subsets of patients with gastric cancer with a more aggressive phenotype." (PMID 24023813, 2013). "Cytoplasmic immunoreactivity of Legumain was over-expressed in gastric cancer compared with paired normal gastric mucosa." (PMID 24023813, 2013). "Our previous research indicates that LGMN is highly expressed in gastric cancer and correlates with poor prognosis; however, the biological functions of LGMN in gastric cancer are largely unknown." (PMID 39065799, 2024). "Together, these study results suggested that LGMN+ TAMs, which may serve as a potential target for GC treatment, promoted gastric cancer cell proliferation and angiogenesis in vitro and in vivo." (PMID 31892854, 2020). "In addition, in vivo experiments suggested that the growth and angiogenesis of gastric cancer tumors were suppressed by knocking down the expression of LGMN in TAMs." (PMID 31892854, 2020). "Previous work have shown that legumain might be an important marker since it is universally overexpressed in metastatic gastric cancer patients." (PMID 30246786, 2018). "Given that legumain has been shown to be overexpressed in different metastatic cancers, it is imperative to define precise mechanism that regulates miR-3978 expression in gastric cancer patients with peritoneal metastasis." (PMID 29138420, 2017). "However, during gastric cancer progression miR-3978 expression is suppressed resulting in concomitant increase in legumain expression." (PMID 27793040, 2016). "We propose that Legumain over-expression may contribute to increased proliferation and the development of gastric cancers." (PMID 24023813, 2013). "Our data showed Legumain expression as an important predictor for metastasis in gastric cancer." (PMID 24023813, 2013). "In order to further clarify the biological function of secreted LGMN (sLGMN) in gastric cancer immune evasion, the levels of LGMN in seven GC cell lines (HCG27, BGC823, MKN45, MKN28, SGC7901, AGS, MGC803) were examined by Western blot." (PMID 39065799, 2024). "In our study, the expression of E-cadherin was also decreased in Cslegumain-transfected RBE cells, indicating that Cslegumain might increase RBE cell motility through downregulation of E-cadherin, which showed the same regulation as legumain to E-cadherin in gastric cancer." (PMID 36797792, 2023). "Since we earlier showed that legumain expression is post-transcriptionally downregulated by miR-3978 in normal peritoneum and is deregulated during metastatic progression, we were interested in defining the post-transcriptional landscape during peritoneal metastasis progression of gastric cancer." (PMID 30246786, 2018). "The aim of the present study was to test this hypothesis by examining expression of Legumain in primary gastric cancers, normal mucosa, and lymph nodes metastasis, and to determine the relationships between Legumain expression and various clinicopathologic and biological variables." (PMID 24023813, 2013).